MMP12 (matrix metallopeptidase 12)
Diseases named in the same sentence as MMP12 in open-access papers (continued):
Sharing a sentence is not in itself a finding about the gene and the disease.
tumor (190 papers, 2002 to 2025). "Research has linked MMP12 to tumor cell invasion, angiogenesis, and metastasis by breaking down physical barriers within the tumor microenvironment." (PMID 41465234, 2025). "Elevated expression of MMP12, largely derived from tumor-associated macrophages, has also been linked to aggressive disease and poor outcomes in UCB." (PMID 41467176, 2025). "In hepatocellular carcinoma (LIHC), the upregulation of MMP12 is associated with tumor growth and progression by promoting angiogenesis, ultimately leading to poorer patient outcomes." (PMID 40244135, 2025). "Matrix Metallopeptidase 12 (MMP12) encodes a metalloproteinase involved in extracellular matrix remodeling within the tumor microenvironment, contributing to cancer invasion and metastasis." (PMID 39744560, 2025). "MMP12 has been implicated in increasing FOXP3 Treg infiltration into tumor tissues, thereby enhancing tumor proliferation and immune evasion in HCC." (PMID 38535990, 2024). "Previous studies showed that MMP12 expression was upregulated in 57 cases of LUSC tissues, and that high expression of MMP12, risk score, age, tumor stage, and TMN stage were significantly associated with prognosis of LUSC patients." (PMID 37601247, 2023). "Recently, MMP12 expression has been shown to be significantly associated with cRCC progression, confirming its involvement in tumour cell migration." (PMID 37439962, 2023). "In line with previous study, we observed that Tregs probe genes expression in tumor was significantly different from non‐tumor, which was also associated with patient poor prognosis, especially Foxp3 and MMP12." (PMID 36226375, 2023). "In multivariate Cox regression analysis a weak to strong MMP12 expression indicated a 2.4–2.8 times higher risk of postoperative tumour relapse (p < 0.001; p < 0.003, respectively)." (PMID 34894337, 2022). "In another study, it was revealed that MMP12-deficient mice accumulated myeloid-derived suppressor cells, which contributed to tumour growth." (PMID 36077754, 2022). "In a clinical study, DRP1 expression was associated with FOXM1 and MMP12 expressions in HNC tumor tissues." (PMID 35313071, 2022). "Matrix metalloproteinases 12 (MMP12) has been associated with tumor cancer progression with its implications in modulation of tumor environment through degradation of extracellular matrix." (PMID 35158756, 2022). "MMP12, also called metalloelastase, was reported to be associated with both reduced tumor growth and increased overall survival." (PMID 34804973, 2021). "In order to deliver the anti-tumoral MMP12 into the tumor mass, we produced a lentivirus encoding MMP12 and then we infected commandos ECFCs." (PMID 25003596, 2014). "The aim of our study is to inhibit cancer progression by engeneering ECFCs, a subset of EPC, with a lentivirus encoding the anti-tumor uPAR-degrading enzyme MMP12." (PMID 25003596, 2014). "On the other side, ECFCs, engineered with a lentivirus encoding MMP12, have been used as carriers of the anti-tumor uPAR-degrading enzyme." (PMID 25003596, 2014). "Notably, MMP12 is expressed not only by tumor cells but also by tumor-associated macrophages, contributing to the dynamic interaction between the tumor and its microenvironment." (PMID 41465234, 2025). "Notably, integrin β6 also showed lower sensitivity to cleavage by the tumour‐associated matrix metalloproteinase MMP‐12, in contrast to integrins β1 and β5, supporting its resilience to proteolysis in tumour‐relevant conditions." (PMID 40488391, 2025). "For instance, matrix metalloproteinases (MMP1, MMP3, MMP10, MMP12), while traditionally associated with promoting tumor cell invasion and metastasis, have been shown in recent studies to facilitate ferroptosis in the right context by inducing lipid peroxidation." (PMID 39372411, 2024). "Dysregulated pathways such as the S100 family, tumor microenvironment and IL-33 signaling that contain MMP12 with high diagnostic ability may have functional relevance in AD’s pathology." (PMID 39338214, 2024).
tumor (continued). "Based on the TIMER algorithm, we found that MMP12 expression was significantly negatively correlated with tumor purity (ρ < 0, p < 0.001) and that upregulation of MMP12 expression was associated with increased infiltration levels of five immune cell types (except CD4+ T cells) (ρ > 0, p < 0.05)." (PMID 37601247, 2023). "The high expression of MMP12 in LUSC might act as an antigen-presenting cell–associated tumor neoantigen and activate the body’s immune response." (PMID 37601247, 2023). "This suggested that the high expression of MMP12 in LUSC might act as an antigen-presenting cell–associated tumor neoantigen and activate the body’s immune response." (PMID 37601247, 2023). "To explore the possible function of MMP12 in ESCC progression, we performed KEGG assays, which revealed that the genes associated with MMP12 were mainly enriched in several tumor-related pathways including PI3K-Akt signaling, estrogen signaling, and relaxin signaling." (PMID 35265129, 2022). "Notably, overexpression of MMP-12 is associated with reduced tumor growth rates in mice, leading to a favourable outcome." (PMID 25003596, 2014). "Interestingly, an association between increased VEGF and MMP-12 gene expression and tumour vascularity has been demonstrated." (PMID 26316944, 2014). "Accordingly, ADAMTS13 and MMP12 demonstrate robust expression at both the mRNA and protein levels in tumor tissue when compared to matching non‐neoplastic tissue." (PMID 41211185, 2025). "ADAMTS13 (p = 0.002), SERPINA12 (p = 0.0186), and MMP12 (p = 0.0049) showed significantly increased expression at the mRNA level in the majority of tumor tissues compared to non‐neoplastic tissue." (PMID 41211185, 2025). "MMP12 overexpression also rescued the defects in inducing tumor proliferation, migration, and invasion by siSRC‐1‐TAMs." (PMID 40985319, 2025). "The authors observed that the proportion of MMP12+ TAMs gradually increased across normal tissues, tumor tissues, and liver metastatic samples." (PMID 40191203, 2025). "MMP12's impact on the immune response within tumors can also contribute to an immunosuppressive environment that favors tumor growth." (PMID 39744560, 2025). "MMP12 secretion at nerve‐tumor interfaces degrades the neural ECM (e.g., elastin), facilitating cancer cell invasion along axons." (PMID 40985319, 2025). "Our results indicated that MMP12 overexpression rescued the tumor PNI capability induced by siSRC‐1‐TAMs." (PMID 40985319, 2025). "Consistent with the mRNA expression data, analysis of the same samples at the protein level also showed elevated expression of ADAMTS13 and, to a lesser extent, MMP12 in tumor tissue." (PMID 41211185, 2025). "It is known that matrix metalloproteinases (MMPs), including MMP7, MMP9, and MMP12, are secreted by both tumor and stromal cells, and they function to regulate metastasis by degrading extracellular matrix." (PMID 40750784, 2025). "The SRC‐1/STAT1/MMP12 axis promotes TAM polarization toward a pro‐tumor M2 phenotype, facilitates cancer cell proliferation, migration, and invasion, and ultimately accelerates PNI progression." (PMID 40985319, 2025). "Using Monocle2 to construct the differentiation trajectory of MMP12+ macrophages revealed that, with the progression of pseudotime, the proportion of these cells increased in both tumor and liver metastatic samples." (PMID 40191203, 2025). "An increase in the level of aromatase in PC3 cells can promote an increase in endogenous estrogen levels and enhance the expression of MMP-12 through the ERα pathway, thus promoting tumor metastasis." (PMID 38511770, 2024). "These myofibroblasts seemed to orchestrate the chemoattraction of MMP12+ macrophages into the tumor milieu via the CCL8-CCR1 signaling axis." (PMID 39528470, 2024). "The MMP-12 protein participates in inflammatory processes and is a vital regulator of tumor growth and occurrence." (PMID 38511770, 2024).
tumor (continued). "Aromatase-induced endogenous estrogen enhances MMP12 expression via Erα, which promotes to the progression and tumor metastasis in CRPC." (PMID 38887275, 2024). "Utilising single-cell RNA-sequencing data of an autochthonous murine model of UBC, Mmp12 mRNA expression was attributed to tumour-infiltrating macrophages." (PMID 37391708, 2023). "Further, the effect of different clinical indicators (gender, age, tumor stage, node stage, metastasis stage, pathologic stage, and MMP12 expression level/value on the OS of LUSC patients was investigated by establishing Cox regression analysis." (PMID 37601247, 2023). "Tumor‐associated marker expression was significantly different among all cell types for MMP2, MMP7, MMP9, MMP12, ABHD5, ADAMTS1, AP‐1, and MGLL each with p < 0.001." (PMID 38037545, 2023). "Proinflammatory CD80, CXCL10, anti‐inflammatory IL‐10, and the tumor‐associated markers MMP2, MMP7, MMP12, and MGLL showed lower baseline expression and were upregulated in macrophages as well." (PMID 38037545, 2023). "MMP12 is involved in the genesis and progression of tumours, specifically in the proliferation, migration, invasion, and metastasis of cancer cells." (PMID 36902078, 2023). "Multivariate Cox regression analysis showed that MMP12 expression was an independent prognostic factor for tumor recurrence-free interval." (PMID 36650426, 2023). "Increasing MMP12 expression was also demonstrated in a variety of tumour and inflammatory tissues compared to normal tissues." (PMID 36902078, 2023). "Single-cell transcriptomics analyses indicated tumour-infiltrating macrophages as a putative source of MMP12." (PMID 37391708, 2023). "High MMP12 mRNA levels correlate with reduced survival in NSCLC and MMP12 promotes tumor growth in an orthotopic mouse model." (PMID 37324952, 2023). "Single-cell transcriptomic analysis of murine tumours further corroborated the source of human tumour-derived MMP12 expression to macrophages, as also murine Mmp12 expression was mapped to macrophages." (PMID 37391708, 2023). "Both IgG1 and IgG4 are cleaved within the lower hinge by a number of inflammatory and/or tumor associated proteases -MMP-3 and MMP-12 at one site, Cathespin at a second site and by MMP-7/pepsin at a third site." (PMID 37713423, 2023). "rWISP-1 also blocked signaling pathway activation and the protein expression of MMP2 and MMP12 in CD326+ tumor cells and reduced the mRNA expression levels of CAF activation markers in Thy1+ CAFs." (PMID 36241874, 2022). "A high expression level of MMP12 in HCC can promote tumor FOXP3+ regulatory T cell infiltration and contribute to a poor prognosis." (PMID 35932027, 2022). "High levels of MMP-12 were found in the saliva of patients with various forms of cancer, which made it a possible candidate for tumor screening." (PMID 36547091, 2022). "MMP12 was highly expressed in various tumor cell comparisons with normal epithelial cells and positively correlated with cancer cell invasion." (PMID 36106139, 2022). "Currently, it is believed that its expression function is bidirectional, that is, MMP12 expression in the tumor periphery can inhibit tumor growth while in the tumor, the expression promotes tumor growth." (PMID 36387195, 2022). "S100A2, S100P and MMP12 were all over expressed in tumor tissues based on paired (P < 0.01) and unpaired expression analysis (P < 0.001)." (PMID 35831362, 2022). "Subsequent Kaplan–Meier analysis revealed that patients with MMP12 positive tumours exhibited a significantly shorter tumour-free survival (p < 0.001)." (PMID 34894337, 2022). "S100P, S100A2 and MMP12 were expressed higher in tumor tissues, compared with normal tissues (P < 0.001), while the opposite was true for DEFA5 expression (P < 0.05)." (PMID 35831362, 2022). "At the same time, MMP-12 produced by macrophages that infiltrate tumor cells degrades plasminogen to produce angiostatin." (PMID 35371322, 2022).
tumor (continued). "MMP12 is expressed in a variety of tumors and can affect the tumor inflammatory response by affecting the secretion and expression of macrophages." (PMID 36387195, 2022). "These discrepant results indicate that the biological function of MMP12 in tumor progression differs between specific tumor cell types." (PMID 35313071, 2022). "Our study shows that it exists the crosstalk between cancer cells and macrophages in muscle tissues that tumor cells secrete IL-6 inducing macrophages to up-regulate MMP12." (PMID 34863141, 2021). "Instead, serotonin increases angiogenesis by decreasing matrix metalloproteinase 12 (MMP12) expression in tumor-infiltrating macrophages." (PMID 33859748, 2021). "Tumor EVs induced expression in macrophages of pro-invasive markers Ccl7, Tnfr2, Mmp12, and Slpi compared to an M-CSF only control." (PMID 34298673, 2021). "In experimental settings, MMP-12 has been shown to promote tumorigenesis by stimulating propagation of tumor cells and tumor growth." (PMID 34912233, 2021). "A study involving a mouse model of tumor allograft showed that serotonin is a regulator of angiogenesis by suppressing MMP-12 expression in tumor-infiltrating macrophages, thus inhibiting angiostatin, an angiogenesis suppressor in solid tumors." (PMID 33525332, 2021). "The transcription factor AP1, which consists of c-Jun and c-Fos, plays an important role in controlling MMP1, MMP9, and MMP12 expression in tumor cells." (PMID 33958583, 2021). "This study validated MMP-12 as a significant prognostic biomarker in this rare and aggressive tumor." (PMID 33892690, 2021). "Lastly, we think that it exist the crosstalk between cancer cells and macrophages in muscle tissues, it is that tumor cells secrete IL-6 inducing macrophages to up-regulate MMP12 which degrade insulin and IGF-1 in muscle tissue." (PMID 34863141, 2021). "In TAMs compared to non-tumor macrophages, MMP12, a protease involved in macrophage migration and the regulators of lymphocyte homing and inflammation ENPP2, MERTK and F13A1 were upregulated." (PMID 33918618, 2021). "A recent study showed that overexpression of MMP12 was identified in cohorts of resectable tumor tissues compared with normal squamous epithelium, and overexpression of MMP12 was correlated with poor overall survival in ESCCs." (PMID 33935718, 2021). "The results corroborate the results of our study in which MMP-12 levels are affected in the presence of tumor." (PMID 33892690, 2021). "In our study, the data shows that the crosstalk between cancer cells and macrophages in muscle tissues is that tumor cells secrete IL-6 inducing macrophages to up-regulate MMP12." (PMID 34863141, 2021). "In HCC, MMP-12 overexpression has been correlated with tumor size, AFP and poor overall survival, suggesting MMP-12 as an independent prognostic predictor for HCC." (PMID 32414178, 2020). "Expressions of MMP12 and SULF1 were associated with tumor progression or metastasis in COAD, HNSC, LUAD, and LUSC." (PMID 33324676, 2020). "According to another study, EGCG decreased MMP-2 expression through JNK signaling and inhibited MMP-7, MMP-9, and MMP-12 in tumor tissues." (PMID 33113766, 2020). "We chose IdeS as a model protease and MMP12, secreted by macrophages in the tumor microenvironment or in chronic inflammatory diseases, as a more relevant pathophysiological protease." (PMID 32117299, 2020). "MMP-2, MMP-7, MMP-9, and MMP-12 belong to metalloproteinases (MMPs), a family of zinc-binding enzymes related to tumor invasion and angiogenesis." (PMID 33113766, 2020). "In malignant melanoma cell lines with high reactive oxygen species (ROS), TAMs increased gene expression of mmp2, mmp9, mmp12, and ctsl proteases known to contribute to tumor invasiveness." (PMID 31737559, 2019). "In contrast to MMP12 as tumor suppressor, as reported by a previous study, our prognostic analysis showed that MMP12 was protective against GBC (P = 0.006)." (PMID 31119098, 2019).
tumor (continued). "We used IHC methods to determine LIFR, PIK3R1, and MMP12 protein expression in 20 GBC tumor tissues and patient-matched adjacent peritumor tissues." (PMID 31119098, 2019). "GO/KEGG analysis evidenced a significant enrichment of terms related to Th17 lymphocytes and in the KRAS-mutants enriched cluster the upregulation of IL6 and MMP12 has been detected, confirming the crosstalk between tumor and Th17 cells." (PMID 31405063, 2019). "These discrepant results suggest that the role of MMP12 in cancer progression differs between tumor or cell types." (PMID 31119098, 2019). "TNM stage, tumor grade, postoperative adjuvant therapy, TPX2 expression and MMP12 expression were all associated with OS (P < 0.05)." (PMID 30305064, 2018). "The survival prediction model consisting of two genes (TPX2 and MMP12) and two clinicopathological factors (tumor stage and grade) was developed." (PMID 30305064, 2018). "Univariate Cox analysis showed that TNM stage, tumor grade, postoperative adjuvant therapy, TPX2 expression and MMP12 expression were significantly associated with DFS (P < 0.05)." (PMID 30305064, 2018). "In the carcinoma cells, TPX2 staining was mainly found in the nuclei, while MMP12 expression was mainly observed in the cytoplasm of tumor cells." (PMID 30305064, 2018). "Only SPP1 and MMP12 were also present in the whole tumour signature, suggesting that these targets are also abundantly expressed in other cell types, in addition to ECs." (PMID 28487489, 2017). "MMP12 was also clearly expressed (although at low levels) in whole tumour samples confirming that MMP12 is also expressed in other cell types in addition to ECs, as previously discussed." (PMID 28487489, 2017). "This corresponded to normal tissue (n=4), tumour tissue (n=4), NEC (n=1), TEC (APLN n=4, MMP12 n=3), isolated normal epithelial cells (n=4) and tumour epithelial cell samples (n=4), which were isolated following the same approach." (PMID 28487489, 2017). "Contrary, we observed a higher relative serum expression of MMP12 in patients with vascular invasion (V1-stage) compared to V0-staged patients suggesting a tumor promoting role of serum MMP12." (PMID 27431388, 2016). "In animal models of melanoma, delivery of specific MMP-12 by such EPCs has been shown to induce cleavage of molecules that induce tumor progression, thus inhibiting tumor growth, angiogenesis, and metastasis." (PMID 26000021, 2015). "This treatment also induced the down-regulation of MMP12, which is in agreement with full length uPAR-dependent tumor malignancy, thus confirming a “protective role” of MMP12 in cancer invasivity." (PMID 25003596, 2014). "In the CD11b+ c26GM tumor splenocytes (group 1) MMP-12 (macrophage elastase) and a leukocyte elastase are predicted to have the greatest functional input among other proteases (MMP-12, leukocyte elastase)." (PMID 25294811, 2014). "Several MMPs, including MMP12, display a protective effect by suppressing tumor growth, thus accounting for the failure of clinical trials which employed broad-range MMP inhibitors." (PMID 25003596, 2014). "The anti-tumor and anti-angiogenetic activity of MMP-12 is often ascribed to the generation of angiostatin from plasminogen." (PMID 25003596, 2014). "Here we manipulated ECFCs, a sub-type of EPCs, as cellular vehicle to deliver MMP12 into the tumor mass with the aim to truncate uPAR both in endothelial and tumor cells." (PMID 25003596, 2014). "In vivo MMP12-engineered ECFCs cleaved uPAR within the tumor mass and strongly inhibited tumor growth, tumor angiogenesis and development of lung metastasis." (PMID 25003596, 2014). "In general, our IHC data demonstrated that the NPC tumor cells expressed higher levels of MMP12 compared to adjacent normal cells." (PMID 24885469, 2014). "MMP-12 is released by AMs and favours tumour progression by enhancing angiogenesis and the breakdown of elastin." (PMID 26316944, 2014).